PLEC (plectin)
Diseases named in the same sentence as PLEC in open-access papers (continued):
Sharing a sentence is not in itself a finding about the gene and the disease.
cancer (continued). "Since a symbiotic relation between invadopodia and exosome secretion resulting in increased invasion of cancer cells has been identified, plectin-mediated IF–actomyosin interplay could constitute an important regulatory element in tumor progression." (PMID 34440923, 2021). "Interestingly, there was a predominant pattern of amplification in ovarian (26%), esophageal (12.6%), and pancreatic (8.1%) cancer, which coincides with previous reports of plectin overexpression in these malignant tissues." (PMID 34571895, 2021). "In addition, the breast cancer susceptibility protein, BRCA2, interacts with PLEC, where the BRCA2/PLEC complex is involved in nuclear duplication and centrosome formation." (PMID 34001250, 2021). "In accordance, plectin is upregulated in highly metastatic and invasive cancer cells." (PMID 34571895, 2021). "Moreover, recent studies have revealed the anti-cancer effect of direct therapeutic targeting of CSP and plectin, opening new avenues of research into CSP’s and plectin’s role in cancer." (PMID 34571895, 2021). "Given that anti-plectin drugs have been shown to stimulate the immune system against cancer cells, such combination strategies may be able to induce more lasting remissions and have a more substantial impact on metastases than current treatment regimens." (PMID 34571895, 2021). "Identified plectin mutations were sporadic, with no clear mutation hotspot, suggesting that mutation is likely not a major driver of plectin’s differential role in cancer." (PMID 34571895, 2021). "Studies showed that plectin was related to cancer progression and metastasis." (PMID 32670437, 2020). "Experimental evidence supporting the plectin in animal models suggests that some human cancers could also be related to plectin and hence could be treated by targeting plectin." (PMID 32670437, 2020). "Furthermore, PCS2 can readily be used as a potential tool to isolate CSCs and/or other plectin positive cancer cell sub-populations that are metastasizing." (PMID 31628412, 2019). "This all demonstrates plectin’s promotion effect on cancer cell migration and cancer progression." (PMID 29587367, 2018). "As plectin regulates cell migration in a cell-type-dependent manner (Section 3.1), it may also regulate cancer cell migration in this way." (PMID 29587367, 2018). "Although the emerging literature suggests the clinical importance of fascin and plectin on human cancers as potential prognostic markers or therapeutic targets, there are still very little molecular details defining the mechanisms of action of those proteins in the control of oral tumorigenesis." (PMID 29088820, 2017). "The role of plectin-1 and DLCs in cancer development, however, is controversial." (PMID 23209772, 2012). "Consequently, the aberrant subcellular localization of plectin in cancer cells may result from the dysregulation of specific isoforms." (PMID 41011568, 2025). "Finally, given the critical role plectin plays in cell/tissue mechanics, which is a key aspect of epithelial carcinogenesis, it is surprising that only a few studies aiming at elucidating the role of plectin in cancer have been published so far." (PMID 39875099, 2025). "However, the prognostic significance of the PLEC gene appears to be specific to cancer type." (PMID 41011568, 2025). "Since plectin has been shown to be overexpressed in some cancers, it is possible that when cancer cells simultaneously overexpress both vimentin and plectin, they may have more VIFs accumulated at the perinuclear region and thereby tends to undergo nuclear dysmorphia." (PMID 39542246, 2024). "Thus, Plectin targeting might be utilised, as a potential treatment option, to inhibit cancer motility and invasiveness." (PMID 37345897, 2023). "However, additional work is required to understand if the additive effects of plectin mutations and copy number alterations could lead to a pro-tumorigenic phenotype or explain the heterogenous role of plectin in different cancers." (PMID 34571895, 2021).
cancer (continued). "Knockdown of plectin was shown to induce displacement of centrosome and nuclear abnormalities, suggesting that plectin misexpression could play a part in genomic instability and, consequently, contribute to cancer development." (PMID 34571895, 2021). "Knockdown of plectin expression using small interfering ribonucleic acids (siRNAs) impairs the migration, invasion, and adhesion of SW480 cancer cells." (PMID 41169522, 2025). "In basal-cell carcinoma (BCC), plectin expression is significantly reduced compared with that of normal skin, while squamous-cell carcinoma (SCC) and in situ carcinoma show a mild decrease." (PMID 39334817, 2024). "Apart from these markers, Plectin (PLEC) and Profilin 1 (PFN1) that are previously reported as metastasis regulators in different cancers, showed differential expression in our study." (PMID 37770851, 2023). "This new avenue of research is widening our anti-cancer repertoire and utilizing a pharmacological approach to interrogate plectin’s and CSP’s function in cancer." (PMID 34571895, 2021). "Alternatively, plecstatin-1, an organoruthenium drug candidate that selectively targets plectin and CSP, has been identified as a promising anti-cancer strategy." (PMID 34571895, 2021). "CSP inhibition recapitulated the anti-cancer effects seen from plectin knockout studies, seemingly implicating CSP as a potent mediator of plectin’s protumorigenic function." (PMID 34571895, 2021). "In PDAC cells, incubating plectin-rich exosomes with CSP-negative cells conferred CSP expression and increased cancer cell migration and invasion capacity." (PMID 34571895, 2021). "For PLEC and EPPK1, 19 datasets show increased expression in cancers, while only 8 datasets and 7 datasets demonstrate decreased expression of PLEC and EPPK1 in cancers, respectively." (PMID 29587367, 2018). "The down regulation of plectin gene PLEC1 by siRNA promotes the migration and invasion of the MDA-MB-231 cancer cells." (PMID 25566531, 2014). "The expression of plectin commences in the early stages of carcinogenesis in IPMN, which may aid in the early detection of malignant tumors." (PMID 39334817, 2024). "Taken together, our findings suggest that the ΔNp63α/PLEC/NRF2 signaling pathway and antioxidant defenses could be targeted as promising therapeutic approaches for cancer treatment." (PMID 39500864, 2024). "Furthermore, quantitative proteomic analysis identified plectin as a potential biomarker in esophageal squamous-cell carcinoma (ESCC), emphasizing its crucial role in this cancer development." (PMID 39334817, 2024). "Although plectin is not annotated as a surface protein, it has been shown to have aberrant localization to the cell surface in some cancers." (PMID 38053024, 2023). "PLEC, a member of the Plakin family of proteins and a cytoskeletal linker, modulates protein kinase C signalling and mitogen‐activated protein (MAP) kinases involved in cellular stress responses and migration in cancer." (PMID 37378426, 2023). "Such particles have a high affinity for cancer-specific plectin (CSP) and accumulate within tumors but not in normal pancreatic tissue." (PMID 36612146, 2022). "Among these genes, EEF1A1, PLEC, and TCEB1 are common cancer-related genes." (PMID 35126520, 2022). "Studies have found that plectin affects cancer cell invasion and metastasis, but the exact mechanism is not fully understood." (PMID 36613521, 2022). "Moreover, in HNSCC, the ablation of plectin by siRNA suppressed cancer cell proliferation and reduced phosphorylation of ERK1/2 signaling, potentially resulting from plectin’s interaction with integrin β4." (PMID 34571895, 2021). "Several proteins involved in cytoskeleton rearrangement such as actin, TNS3, KIF23, CKAP2L, NEDD9 and PLEC were also hyperphosphorylated, indicating the known regulatory role of AXL in promoting cancer cell migration/invasion and inducing epithelial-mesenchymal transition (EMT)." (PMID 34439388, 2021).
cancer (continued). "For example, PLEC, ANXA10, EHF, SLC4A, and CUL4A are expressed at high levels in MDA-MB-231 relative to MCF-7 cells, and MAGED1, SYK, and EPCAM are expressed at higher levels in triple-negative cancer tissues relative to non-invasive control tissues." (PMID 26053433, 2015). "Taken together, these results demonstrate that knockdown of plectin and vimentin decreases the motility of PC3 cell lines thus, supporting previous reports that down-regulation of these proteins is involved in invasion and migration important initial steps in cancer metastasis." (PMID 23717685, 2013). "In addition, surface-targeting peptides that bind to plectin, such as a peptide derived from Cyclin D2 (Pep5) and a highly CSC-specific hit peptoid (PSC2), exhibit high binding specificity and have been shown to inhibit tumor growth or induce cancer cell death." (PMID 41011568, 2025). "Importantly, we identified several biotinylated peptides derived from plectin and nucleolin, both of which are not annotated in surface proteome databases but have been shown to have aberrant surface localization in certain cancers highlighting the utility of this method." (PMID 38053024, 2023).
tumor (48 papers, 2013 to 2025). "Similar to our observation in tumor formation in vivo, plectin-deficient cells formed larger spheroids than the control cells." (PMID 36038818, 2022). "An increasing number of reports have implicated plectin as a regulator of malignant phenotypes and cross-talk with the tumor microenvironment, in part due to its function as a cytoskeletal linker and signaling scaffold." (PMID 34571895, 2021). "One of the ‘hit’ peptoids bound to plectin, a structural protein, predominantly expressed intracellularly, but whose localization on the cell surface is linked to tumor invasion and metastasis." (PMID 31628412, 2019). "In vivo phage display has been utilized previously to map vascular signatures and identify novel tumor-associated proteins, such as proteome activator complex 28 and plectin-1." (PMID 26045973, 2014). "In addition, plectin has increasingly been implicated as a key mediator of tumor–stroma interactions, contributing to the resistance and remodeling of the TME and fostering a pro-tumorigenic niche." (PMID 41011568, 2025). "In this model, plectin deficiency suppresses tumor initiation and growth." (PMID 40052672, 2025). "Although multiple reports have linked plectin with tumor malignancy and other pathologies, mechanistic insights into how plectin functionally contributes to carcinogenesis remain largely unknown." (PMID 40052672, 2025). "Moreover, following bacillus calmette guerin treatment, increased plectin levels were associated with elevated PD-L1 expression in an immune-activated tumor context, further supporting its role in immune modulation." (PMID 41011568, 2025). "Since then, plectin has been implicated as a pro-tumorigenic regulator with its ablation resulting in inhibited cell proliferation, migration, and invasion in vitro and reduced tumor volume and metastatic burden in vivo." (PMID 34571866, 2021). "In human HCC, deficiency in plectin may create more free integrin FnIII domains adapting for active FAK that is required for macromolecular assembly prior to tumor cell migration." (PMID 25774093, 2015). "Additionally, the depletion of vimentin in OSCC-derived cells resulted in an augmented interaction with integrin β4, suggesting that high levels of plectin expression in OSCC may be associated with tumor development." (PMID 39334817, 2024). "Here, using liver-specific PlecΔAlb knockout mice, we show that plectin ablation in hepatocytes significantly reduced tumor burden in a model of DEN-induced HCC, which mimics fundamental aspects of human disease." (PMID 40052672, 2025). "Beyond its structural roles, plectin integrates these structural and mechanical cues with signaling pathways to drive tumor growth and metastasis." (PMID 41011568, 2025). "To identify potential molecular effectors and signaling pathways mediating the tumor suppressive effects of plectin inactivation, we profiled the proteomes of WT, KO, and PST-treated WT SNU-475 cells using MS-based shotgun proteomics and phosphoproteomics." (PMID 40052672, 2025). "These plectin-positive exosomes can enhance tumor growth even in recipient cells that lack plectin expression on their surface." (PMID 41011568, 2025). "(F) Relative plectin (PLEC) mRNA expression in samples collected from HCC patient meta-cohort clustered based on tumor, node, metastasis (TNM) classification (stage I-IV)." (PMID 40052672, 2025). "Tumor, node, metastasis (TNM) classification of an HCC meta-cohort with clinically annotated tumors from HCC patients (n=978) demonstrated that high PLEC mRNA expression is associated with advanced TNM stages." (PMID 40052672, 2025). "Collectively, these observations demonstrate the functional significance of plectin mislocalization in promoting tumor progression." (PMID 41011568, 2025). "Thirdly, the mislocalization of plectin has been identified as a crucial factor in promoting tumor growth." (PMID 41011568, 2025).
tumor (continued). "This pattern was further supported by immunohistochemical analysis of five HCC cases, which showed markedly reduced plectin expression in tumor regions." (PMID 41011568, 2025). "In this study, our analysis of tissue microarrays revealed a significantly higher expression level of PLEC in OC tumor tissues compared to normal tissues, providing further evidence for the involvement of PLEC in OC progression." (PMID 39915800, 2025). "In this review, we summarize the oncogenic roles of plectin dysregulation in tumor growth, metastasis, and its bidirectional interplay with the TME." (PMID 41011568, 2025). "Our study also confirmed that circulating tumor cells in the blood of patients with PDAC express Plectin-1 at a very high frequency." (PMID 39843495, 2025). "Researchers have identified plectin as a biomarker for circulating tumor cells in portal and peripheral blood samples and found plectin-positive circulating tumor cells in 43.8% and 50% of portal and peripheral blood samples, respectively." (PMID 41169522, 2025). "Collectively, these findings highlight the crucial role of plectin dysregulation in sustaining proliferative signaling essential for tumor growth." (PMID 41011568, 2025). "Studies have shown that plectin dysregulation contributes to tumor progression through multiple mechanisms, such as promoting tumor growth, enhancing metastatic potential, and contributing to therapy resistance." (PMID 41011568, 2025). "The discovery of CSP underscores the pathological mislocalization of plectin and provides a promising avenue for tumor detection and targeted therapy." (PMID 41011568, 2025). "Consistent with our in vitro observations, MRI analysis at 4, 6, and 9 wk post-induction revealed that both genetic and pharmacological plectin inactivation results in a substantial reduction in the average tumor number per mouse and the tumor incidence." (PMID 40052672, 2025). "For example, in basal and squamous cell carcinomas, plectin is expressed at lower levels in tumor tissues compared to normal skin tissue as a component of HDs." (PMID 41011568, 2025). "IHC analyses revealed a marked upregulation of PLEC in tumor tissues from the patient with all four BC subtypes when compared to controls." (PMID 39695149, 2024). "Up to now, plectin has been found to be abnormally expressed in various types of tumors, indicating a potential key role of plectin in tumor onset and progression." (PMID 39334817, 2024). "Initially, plectin’s recruitment to the plasma membrane by integrin α6β4 mediates tumor suppression." (PMID 39334817, 2024). "Here we reported for the first time that EpOME treatment markedly enhanced TNBC cell proliferation, migration, and invasion, as well as promoting tumor growth and lung metastasis in mice via upregulation of PLEC." (PMID 39695149, 2024). "Plectin actively participates in numerous cellular activities that contribute to tumor initiation and progression, including cell proliferation, adhesion, migration, invasion, and signal transduction." (PMID 39334817, 2024). "Compared with normal epithelial cells, the expression level of plectin is further elevated in OSCC tumor tissues." (PMID 39334817, 2024). "The most interesting results are the significant decrease in PPL and PLEC expression in Type II compared to Type I tumours." (PMID 39682273, 2024). "In recent years, more and more studies have reported that plectin is closely related to tumorigenesis and development, exhibiting both tumor-suppressive and tumor-promoting functions." (PMID 39334817, 2024). "Subsequently, by using transcriptomics and proteomics techniques, CXCL9 and PLEC were respectively located as the key factors for the tumor-promoting effect of EpOMEs in TNBCs." (PMID 39695149, 2024). "The data demonstrated a distinct accumulation of [99mTc]Tc-HYNIC-PTP in five types of tumor-bearing mice with favorable biodistribution and pharmacokinetics, and tumor uptake correlated with their plectin expression levels." (PMID 35631582, 2022).